MUC1 (mucin 1, cell surface associated)
Diseases named in the same sentence as MUC1 in open-access papers (continued):
Sharing a sentence is not in itself a finding about the gene and the disease.
lung carcinoma (continued). "Thus, evaluating the prognostic significance of MUC1 in lung cancer is a very significant task." (PMID 40655139, 2025). "The significant upregulation of MUC1 expression in LUAD has important clinical implications, as it may serve as a diagnostic marker and guide personalized treatment strategies for this subtype of lung cancer." (PMID 40655139, 2025). "M-DCsTNF could also be used to treat pancreatic or lung cancers because they also overexpress Muc1." (PMID 39105847, 2024). "In the chemotherapy resistance of lung cancer, miR-551b promotes the sensitivity of cells to apoptotic toxicity induced by chemotherapeutic agents by reducing the expression of cell catalase, inhibiting the accumulation of reactive oxygen species and the expression of MUC1 protein." (PMID 38572416, 2024). "Thus, we have found a new compound to block MUC1-CT in lung cancer cells that might apply to many other types of cancers." (PMID 36810913, 2023). "Besides JAK1, mutant EGFR mediates MUC1-CT expression in the transgenic lung cancer mouse model." (PMID 36810913, 2023). "Moreover, the depolarization of cells impacted MUC1 expression in lung cancer progression." (PMID 36059804, 2022). "Moreover, there are reports that a MUC-1-based anti-cancer vaccine was effective against breast, colon and lung cancers: a vaccine made using MUC-1 as antigen elicited adaptive host immunity (B or T cell response) targeting MUC-1-expressing cancer cells, and led to cancer cell death." (PMID 29285261, 2017). "Taken together, the malaria parasite may be an ideal vaccine vehicle not only for presentation of lung cancer antigens (such as MUC1) to tumor-specific T-cells, but also act as an adjuvant to provide the appropriate milieu to enhance the efficacy of these effector cells." (PMID 21931708, 2011). "Thus, expression levels of the different MUC1 isoforms and their epitopes may need to be evaluated to fully explain the increased levels in serum of lung cancer patients." (PMID 16117833, 2005). "A series of antigens targeting surface proteins, including EGFR, CEA, MSLN, HER2, ROR1, MUC1, and DLL3 in lung carcinoma cells have been incorporated into CAR structure to allow CAR-T cells target lung cancer tissue." (PMID 40624569, 2025). "One study identified twelve proteins, such as members of the annexin family (annexin A1, A2, A3, A5, A6, A11), along with PR-OM1, MUC1, BPIFA1, CRNN, MUC5B and IQGAP, which showed significant differences between lung cancer patients and healthy individuals." (PMID 40575159, 2025). "EGFR, MSLN, MUC1, CEA, PD-L1, ROR1, HHLA2 (also referred to as B7H7), HER2, and various other target antigens are being studied for CAR-T therapy in lung cancer." (PMID 38622705, 2024). "Through analysis of an independent lung cancer single-cell dataset, we showed that co-expression of EGFR and MUC1 was specific to tumor cells in the tumor microenvironment." (PMID 39664199, 2024). "In lung cancer, the most relevant therapeutic targets include ROR1, EGFR, PD-L1, CD80/CD86, mucin 1 (MUC1), mesothelin (MSLN), carcinoembryonic antigen (CEA), prostate stem cell antigen (PSCA) and human epidermal growth factor receptor 2 (HER2)." (PMID 36873868, 2023). "CAR-T cells targeting MUC1 successfully eliminate NSCLC tumor cells and are evaluated in clinical trials for lung cancer (NCT03525782, NCT02587689, and NCT05239143)." (PMID 36810079, 2023). "One ambitious trial seeks to test a battery of CAR T cell targets—PSCA, MUC1, TGFß, and GPC3—against advanced-stage lung cancers (NCT03198052)." (PMID 37998743, 2023). "Collectively, our results highlight the new molecular mechanisms of AICAR that target MUC1-CT and its interactions with EGFR and JAK1 and provide a new therapeutic approach against EGFR-mutant lung cancer." (PMID 36810913, 2023).
lung carcinoma (continued). "Recent studies have established that MUC1 or its released fragment, KL6 are prominent membrane markers mediating the expression of anti-inflammatory genes in interstitial lung diseases, asthma, COPD and lung cancer." (PMID 35832493, 2022). "It was shown that MUC1, the most highly expressed MUC in lung cancer, was expressed specifically in invasive lepidic predominant adenocarcinoma (LPA)." (PMID 36059804, 2022). "In lung cancer, TG4010, a modified vaccine targeting MUC1 and interleukin 2, showed improvements in progression‐free survival compared to placebo in a phase 2b/3 trial." (PMID 35102706, 2022). "Meanwhile, an ongoing phase I study is testing safety, efficacy, and tolerance of a combination of CAR-T cells targeting MUC-1 and PSCA in lung cancer (NCT03198052)." (PMID 35720364, 2022). "Subunit vaccine with MUC1 tandem repeats and MBP/BCG adjuvant induced Th1 immune response, activation of NK cells, and MUC1-specific CTL in mouse models of melanoma and lung carcinoma." (PMID 34899753, 2021). "In lung cancer, common targets such as MSLN, MUC1, PSCA, and epithelial cell adhesion molecule, have intratumoral heterogeneity, leading to an unsatisfactory outcome of CAT-T cell therapy in lung cancer." (PMID 34790207, 2021). "CD70, B7-H3, MUC1, PSCA, PD-L1, and CD80/CD86, have exhibited enhanced antitumor efficacy in lung cancer." (PMID 34790207, 2021). "Similar to MUC1, most of the previous studies on MUC4 have been directed at lung cancer whereas investigations into airway disorders are sparse." (PMID 32948202, 2020). "In combination of tumorigenic mechanism and the expression of MUC1 and VEGFR1 in lung cancer, the combined detection of three individual natural autoantibodies is more valuable in early diagnosis of NSCLC." (PMID 32392378, 2020). "Treatment with either dose of 223Ra increased the sensitivity of the breast, prostate, and lung carcinoma cell lines to CTL-mediated lysis targeting the CEA, MUC-1, and brachyury tumor antigens." (PMID 27893426, 2016). "Restoration of miR-145-5p expression using either vorinostat or 5-azacytidine, which released methylation of the miR-145 locus, led to inhibition of migration of lung cancer cells and to down-regulation of OCT-4, MYC, EGFR, MUC-1 and TPD52 expression." (PMID 26440147, 2015). "MUC1, a physiological marker, HIF1A, a regulator of metabolic reprogramming, and NKX2-1, a lineage-specific marker performed well as classifiers of lung cancer and its major subtypes." (PMID 23028920, 2012). "Four proteins were found to be more abundant in the lung cancer samples than those of the controls, namely CRP (13.3 fold), SAA (2.0 fold), AAT (1.4 fold) and MUC1 (1.4 fold)." (PMID 16117833, 2005). "Additionally, proteins such as SHC1, MUC1, and ADAM15 display high betweenness centrality scores, indicating their importance as mediators in lung cancer progression." (PMID 40165937, 2025). "The M1C ADC was active against MUC1-positive, but not MUC1-negative, breast and lung cancer cells; however, it is not known if this agent has activity against CRPC/NEPC cells, particularly in the setting of drug resistance." (PMID 40553569, 2025). "To validate this hypothesis, we performed dual-immunofluorescence staining for MUC1-CT and p-JAK1 to examine whether these two proteins co-localise in lung cancer cells." (PMID 36810913, 2023). "The glycosylated membrane-bound mucin proteins can also be overexpressed in lung cancers; in normal bronchioles and pulmonary submucosa, MUC1 is not expressed at observable levels except on the luminal side." (PMID 37998743, 2023).
lung carcinoma (continued). "For example, it promotes atg4b-mediated autophagy and attenuates sorafenib sensitivity in hepatocellular carcinoma cells; it regulates eIF4A3/MUC1/EGFR signalling and modulates the response of EGFR-mutant lung cancer to EGFR tyrosine kinase inhibitor resistance." (PMID 35359593, 2022). "TAs, such as Survvin, VEGFR (vascular endothelial growth factor receptor), MUC1 (mucin 1) and TTK (TTK protein kinase), were used most extensively as targets for developing peptide‐based therapeutic cancer vaccines, targeting lung cancer, gastrointestinal cancer and melanoma." (PMID 33754407, 2021). "However, several reports suggested that MUC1 was overexpressed in NSCLC and can be used as a suitable biomarker for diagnosis of lung cancer." (PMID 30646616, 2019). "The increase in MUC1 expression with the progression of premalignant lung lesions to invasive carcinoma in patients with NSCLC supports MUC1 as a possible therapeutic target for the prevention and treatment of lung cancer." (PMID 30479696, 2018). "Our demonstration of increased MUC1 expression in invasive and premalignant lesions in paired samples in human NSCLC, along with progression of tumorigenesis, adds to the body of research supporting the role of MUC1 in the development of human lung cancer." (PMID 30479696, 2018). "MUC1 and BMI1 are direct targets of miR-128 in paclitaxel-resistant lung cancer cells." (PMID 29299167, 2017). "The extracellular immunogenic subunit (25 A.A.)of MUC1 combined with the nonspecific adjuvant monophosphoryl lipid A and three different lipids was combined together to prepare a therapeutic lung cancer vaccine called liposomal BLP25 (L-BLP25, Stimuvax)." (PMID 27686848, 2016). "Similarly to the effect of miR-145-5p, selective knockdown of OCT-4, EGFR, MYC, MUC-1 and the newly identified TPD52 impaired migration of lung cancer cells." (PMID 26440147, 2015). "We evaluated a three-protein signature consisting of a physiological protein (MUC1), a cancer-specific protein (HIF1A), and a lineage-specific protein (NKX2-1) that could discriminate lung cancer and its major subtypes with a low failure rate." (PMID 23028920, 2012). "Using RT-PCR, KS1/4 was previously reported to be the most sensitive marker among CEA, CK19, KS1/4, LunX, muc1 and PDEF for the detection of metastatic NSCLC in mediastinal lymph nodes, and LunX was with the second highest sensitivity distinguishing lung cancer from lung benign disease." (PMID 18513434, 2008). "Overexpression of MUC1 and MUC4 in lung carcinomas may further contribute to REM pathogenesis." (PMID 40142939, 2025). "To validate the sequencing results, we selected three genes (MUC1, MYO6, and IGKC) among the 11 important molecular marker candidates for silent transient cell line construction and transferred silent MUC1 and MYO6 into lung cancer cell line A-549, and silent IGKC into normal lung cell HPAEC." (PMID 39991571, 2025). "This MUC1/CD3 bispecific antibody was generated via the connection of an anti-CD3 and anti-MUC1 mAb to a PLGA nanoparticle through a chemical reaction, and this BsAb could also elicit anti-tumor activity in lung cancer samples in another study." (PMID 37489369, 2023). "It is not clear if MUC1 interacts with JAK1 directly in lung cancer." (PMID 36810913, 2023). "We then asked if simultaneously targeting MUC1 and EGFR could improve lung cancer treatment." (PMID 36810913, 2023). "To examine whether the induction of EMT reduces HER2 expression, we analyzed mRNA expression of ERBB2, epithelial phenotype markers CDH1, EPCAM, MUC1 and OCLN, mesenchymal phenotype markers CDH2, FN1, SNAI2, and VIM in the A549 cell line (HER2-high human lung cancer epithelial cell line)." (PMID 34575017, 2021). "However, TAMs also secrete MUC1 to enhance the expression of CSC-related and inflammatory genes in lung cancer cells, such as CD133, SOX2, and NF-κB, thus promoting the generation of lung cancer stem cells (LCSCs)." (PMID 33224886, 2020).
lung carcinoma (continued). "Breast, prostate, and lung carcinoma cells were first exposed to 223Ra for 96 hours, then co-cultured with CD8+ effector T cells specific for carcinoembryonic antigen (CEA; HLA-A2-restricted), mucin-1 (MUC-1; HLA-A2-restricted), and brachyury (HLA-A2/A24-restricted) epitopes." (PMID 27893426, 2016). "We found that MUC1-silenced THP-1 cells could not increase the percentage of CD133+ lung cancer cell populations, unlike their wildtype counterparts, suggesting that MUC1 may be involved in promoting M2-TAM polarization." (PMID 27276704, 2016). "In this regard, MUC1 and EGFR may serve as molecular targets for lung cancer prevention." (PMID 22457794, 2012). "In addition, because combined chemoprevention targeting more than one oncogenic protein could potentiate the cancer preventive activity and reduce toxicity, it would be interesting to determine if a regime targeting both MUC1 and EGFR achieves more effective prevention against lung cancer." (PMID 22457794, 2012). "Although targeting MUC1 and EGFR individually have been proven to be effective in treating a portion of lung cancer patients, chemoprevention against these two factors has not been studied." (PMID 22457794, 2012). "Our western blot data has shown the increased expression of MUC1-CT and decreased expression of ADSL in lung cancer cell lines H1975 and H1650 than in a non-tumorigenic and immortalised lung epithelial cell line AALE, indicating a negative association between MUC1-CT and ADSL expression." (PMID 36810913, 2023). "To determine the differential MUC1 expression between malignant and non-malignant lung tissues, we isolated the tumour nodules and normal lung tissues far (more than 0.5 cm) from visible tumour nodules from the EGFR TL-induced lung cancer mice fed Dox for 14 weeks." (PMID 36810913, 2023).
ovarian carcinoma (161 papers, 2005 to 2025). A malignant neoplasm originating from the surface ovarian epithelium. "CA125 and HE4 are currently used in clinical practice, whereas FOLR1 and MUC1 show promise as diagnostic and therapeutic targets for ovarian cancer." (PMID 40801326, 2025). "MUC1 has been assumed to be a reliable diagnostic marker for ovarian cancer due to its overexpression in metastatic and advanced tumors." (PMID 35054873, 2022). "We evaluated the expression of mucin-1 (MUC1), cytokeratin 8/18 (CK 8/18) and Wilms’ tumor 1(WT-1), all diagnostic markers of ovarian cancer, and vimentin and CD44 were also analyzed." (PMID 32392708, 2020). "MUC1 (also known as CA15.3 or polymorphic epithelial mucin) is a tumor-associated mucin that is over-expressed in most adenocarcinomas, including breast, pancreatic, and epithelial ovarian cancer." (PMID 32429033, 2020). "Tumour associated MUC1 (TA-MUC1), is expressed in >90% of epithelial ovarian cancers and associated with cancer progression properties, such as tumour stage, grade, residual disease status and presence of ascites." (PMID 32937961, 2020). "This vaccine targets MUC1, a tumor-associated antigen that is overexpressed in colorectal, pancreatic, and ovarian cancer." (PMID 30646939, 2019). "Mutations of MUC1 are present in more than 90% of late stage epithelial ovarian cancer patients and are involved in tumor metastasis." (PMID 26863567, 2016). "Both proteins can be mainly overexpressed in serum (CA 15-3 > 20 U/mL, MUC1 > 5 μM) in the presence of breast and ovarian carcinomas; elevated serum concentrations are always associated with a low patient survival rate." (PMID 27490578, 2016). "In conclusion, our study examined four SNPs in MUC16 (CA125) and three SNPs in MUC1 (CA15.3) in relation to ovarian cancer risk and survival in the New England Case-Control study." (PMID 24551091, 2014). "MUC1 is aberrantly upregulated in various malignant epithelial cancers, including ovarian cancer, and is associated with chemoresistance in cancer cells." (PMID 23708102, 2013). "The increased expression of MUC1 and the Lewis y antigen is a significant risk factor for chemoresistance in patients with ovarian epithelial cancer." (PMID 23708102, 2013). "The results show that the stage and expression of MUC1 and the Lewis y antigen were independent risk factors for chemoresistance in ovarian cancer." (PMID 23708102, 2013). "Studies that evaluated the prognostic role of MUC1 in ovarian cancer also found a significant association with clinical-pathological features such as tumour stage, grade, residual disease status and presence of ascites." (PMID 23241107, 2012). "A recent study reported higher anti-MUC1 antibodies were associated with a decreased risk of ovarian cancer among women less than 64 years of age." (PMID 22587442, 2012). "Further research is needed to determine the associations between surgical procedures, anti-MUC1 antibodies, and subsequent ovarian cancer risk." (PMID 22587442, 2012). "In this respect we found that women at hereditary high risk of breast/ovarian cancer with a BRCA1/2 mutation had significantly lower levels of MUC1 IgG ab (p = 0.003) than age-matched healthy controls." (PMID 24212946, 2011). "Recent epidemiological studies describe an association between conditions that induce abs to MUC1 and risk for ovarian cancer, suggesting a protective effect of the immune response on the development of the disease." (PMID 24212946, 2011). "A recent study demonstrated the presence of MUC1 antibodies in blood plasma samples which was inversely correlated with risk of ovarian cancer." (PMID 20034397, 2009). "Mucin 1 (MUC1) is a transmembrane glycoprotein implicated in ovarian cancer biology." (PMID 40277517, 2025). "Interestingly, autoantibodies against aberrantly glycosylated MUC1 have been associated with ovarian cancer, and they have the potential to serve as non-invasive biomarkers for earlier diagnosis of OC." (PMID 40277517, 2025).